RAD50 (RAD50 double strand break repair protein)
Diseases named in the same sentence as RAD50 in open-access papers (continued):
Sharing a sentence is not in itself a finding about the gene and the disease.
colon cancer (8 papers, 2010 to 2024). "Pathogenic variants within MRN complex genes have been implicated in breast, ovarian, prostate, colon cancers and gliomas; however, the hundreds of VUSs within MRE11, RAD50, and NBS1 precludes the application of these data in genetic guidance of carriers." (PMID 36358700, 2022). "For example, the telomerase-positive HCT116 colon cancer cell line used here harbors a mutation in MRE11, which impairs binding to NBS1 and Rad50 and suppresses ATM activation in response to replication stress." (PMID 27602331, 2016). "A previous study showed that this AKT activation has a suppressor role for DNA repair via S6K1, effects accompanied by a reduced expression of MRE11, RAD50, and NBS1 in colon cancer." (PMID 39408794, 2024).
rectal cancer (8 papers, 2017 to 2023). A primary or metastatic malignant neoplasm that affects the rectum. "We recently identified a heterozygous RAD50 I505fs*5 frameshift germline mutation in a 37-year-old man who presented with simultaneous duodenal and rectal cancers." (PMID 37098078, 2023). "Concordant with this previous study, we identified a RAD50 I505fs germline nonsense mutation in the RAD50 gene, indicating an association of RAD50 mutation with the cancers in the 37-year-old patient presented with concomitant duodenal and rectal cancers." (PMID 37098078, 2023). "Low-level expression of RAD50 is associated with poor disease-free survival and OS in early-stage/low-grade rectal cancer patients." (PMID 35656315, 2022). "In a comparison of patients with low vs. high RAD50 expression, we found that low levels of postoperative RAD50 expression in rectal cancer tissues were significantly associated with perineural invasion (p = 0.002)." (PMID 29189711, 2017). "This is a similar result to our finding that low postoperative RAD50 expression was associated with worse DFS and OS in early tumour stage and low-grade rectal cancer." (PMID 32143539, 2020). "We have also found that postoperative expression of RAD50 correlates to patient outcomes in rectal cancer." (PMID 30176843, 2018). "Further investigation of RAD50 in larger populations and the identification of new biomarkers are likely to provide new and effective prognostic tools for rectal cancer management." (PMID 29189711, 2017). "The DFS of rectal cancer patients with low RAD50 expression was worse than the DFS of patients with high RAD50 expression." (PMID 29189711, 2017). "In this study, we aimed to evaluate the prognostic and clinicopathological implication of RAD50 (DNA repair protein RAD50 homolog) expression in rectal cancer." (PMID 29189711, 2017). "We found that low postoperative RAD50 expression was associated with reduced DFS and OS in early tumor stage (T1–2) and low-grade (G1–2) patient subgroups, supporting the potential use of RAD50 as an early prognostic biomarker in rectal cancer." (PMID 29189711, 2017). "In this study, we evaluated RAD50 expression by immunohistochemistry in 266 rectal cancer samples, taking into account several clinicopathological characteristics, as well as the type of treatment received." (PMID 29189711, 2017). "In this study, we evaluated the role of RAD50 as a potential prognostic marker in patients with incident cases of rectal cancer treated with surgery and radiotherapy." (PMID 29189711, 2017). "Based on this premise, we investigated RAD50 as a prognostic biomarker in rectal cancer." (PMID 29189711, 2017). "The status of RAD50 expression may have treatment implications for rectal cancer, particularly for predicting long-term survival of patients with perineural invasion and for potential use in early stage and low-grade rectal cancer assessment." (PMID 29189711, 2017). "However, to date, there is no data available on RAD50 as a specific biomarker in rectal cancer." (PMID 29189711, 2017).
bladder cancer (7 papers, 2008 to 2023). "Another report on 98 patients with bladder cancer showed that mutations in DNA repair genes (CHEK2, ERCC5, GEN1, MLH1, PALB2, RAD50, RAD51B and RECQL4) are associated with an unfavorable cancer prognosis and 22% of patients had a mutation." (PMID 35395863, 2022). "In contrast, our findings suggest that in bladder cancer transcriptional control dominates for RAD50 and NBS1, but MRE11 expression is regulated at the post-transcriptional level." (PMID 24625413, 2014). "For bladder cancer, the expression of the MRE11 subunit was reported to predict radio therapy outcomes, as high expression was associated with better survival, although the role of RAD50 is yet to be elucidated." (PMID 37474724, 2023). "Importantly, here we showed that high RAD21, RAD50 or BARD1 mRNA expression in bladder cancer patients with low-ERBB2 exhibit poor survival." (PMID 37474724, 2023). "Another study showed that with high expression of TRIP13, the expression of γH2A.X decreased and the expression of RAD50 increased in bladder cancer cells after cisplatin treatment, which revealed that TRIP13 promoted DSB repair and reduced apoptosis of cancer cells treated with drugs." (PMID 35601150, 2022). "The expression of ERBB2, RAD21, RAD50 and BARD1 mRNA levels was assessed in The Cancer Genome Atlas (TCGA) bladder cancer dataset along with four validation cohorts." (PMID 37474724, 2023). "In this current investigation we examined RAD21, RAD50 or/and BARD1 co-expression with different status of ERBB2 expression and assessed their prognostic and clinical significance in bladder cancer." (PMID 37474724, 2023). "This study evaluates the biological and prognostic significance of RAD21, RAD50 and BARD1 (homologous recombination biomarkers) mRNA levels with ERBB2 low and high expression to explore their impact on bladder cancer patient survival and cancer aggressiveness." (PMID 37474724, 2023). "Choudhry and colleagues examined protein expression of MRE11, RAD50, NBS1, ATM, and H2AX by immunohistochemistry in pretreatment tumor specimens from 179 bladder cancer patients receiving radical radiotherapy." (PMID 26198537, 2015). "In conclusion, we have found that, in muscle-invasive bladder tumour samples and a panel of bladder cancer cell lines, MRE11 expression is regulated at the post-transcriptional level, while RAD50 and NBS1 undergo transcriptional control." (PMID 24625413, 2014). "MRE11 RNA and protein levels were measured in 88 bladder tumour patient samples, by real-time PCR and immunohistochemistry respectively, and a panel of eight bladder cancer cell lines was screened for MRE11, RAD50 and NBS1 mRNA and protein expression." (PMID 24625413, 2014). "As MRE11, NBS1, RAD50, ATM, and H2AX interact with each other to facilitate DSB damage signalling, we hypothesized that there may be a gene dosage effect in our study, with subjects with increasing numbers of high risk alleles having an increased risk of bladder cancer." (PMID 18638378, 2008). "Hence the RAD50 factor role is yet to be elucidated in different cancer types, in the current study we first assessed the total RAD50 mRNA expression level which was not altered in bladder cancer compared to normal tissues." (PMID 37474724, 2023).
hereditary cancer (7 papers, 2014 to 2023). Malignant neoplasms occurring in families at a rate greater than that expected by chance and caused by germline mutations in a specific gene. "Germline RAD50 mutations may contribute to hereditary cancer in human as hypomorphic RAD50 mutants exhibited cancer predisposition in mice." (PMID 34572942, 2021). "Analysis of hereditary cancer cases (732 BC patients, 189 CRC patients, and 490 cancer-free elderly controls) revealed that 1% presented concurrent germline pathogenic variants in BRCA1, BRCA2, MUTYH, ATM, CHECK2, NBN, and RAD50." (PMID 37628631, 2023).
melanoma (7 papers, 2013 to 2025). A malignant, usually aggressive tumor composed of atypical, neoplastic melanocytes. "While ILF2‐OV induced the upregulation of RAD50, U2AF2 knockdown decreased the RAD50 protein levels in ILF2‐OV melanoma cells." (PMID 34709752, 2021). "In summary, high levels of ILF2‐U2AF2 protein complex control melanoma progression by upregulating the mRNA and protein expression of RAD50 and ATM." (PMID 34709752, 2021). "Accordingly, patients with metastatic stage III melanoma tumours had a significantly higher mRNA expression for RAD50, NBS1, MRE11 and ATM as compared to patients with primary melanoma." (PMID 34709752, 2021). "Consistently, RAD50 knockdown significantly decreased melanoma cell proliferation and colony formation compared to respective control cell lines." (PMID 34709752, 2021). "Along with the elevated RAD50 expression, enhanced ATM and increased p‐ATM levels were observed in metastatic melanoma cells with ILF2‐OV." (PMID 34709752, 2021). "Using RNA‐Seq data from the TCGA SKCM database, RAD50, NBS1, MRE11 and ATM expression were analysed in melanoma tissues." (PMID 34709752, 2021). "Furthermore, we showed that ILF2‐U2AF2 complex enhanced RAD50 and ATM expression in metastatic melanoma cells." (PMID 34709752, 2021).
gastric cancer (6 papers, 2012 to 2022). A primary or metastatic malignant neoplasm involving the stomach. "We also found six genes in MSS tumors (EYS, FAT4, FSIP2, PCDHA1, RAD50, and RECQL4) and two in MSI tumors (EXO1 and FSIP2) that were clonally mutated in multiple patients and have not been previously identified as drivers of gastric cancer or other cancers." (PMID 36970058, 2022).
leukemia (6 papers, 2007 to 2023). A malignant (clonal) hematologic disorder, involving hematopoietic stem cells and characterized by the presence of primitive or atypical myeloid or lymphoid cells in the bone marrow and the blood. "While too few human biallelic RAD50 mutation carriers have been identified to reach a conclusion about their cancer susceptibility, more than 20% of mice homozygous for a hypomorphic Rad50 allele (Rad50 p.Lys22Met) that lived past age four months died with lymphoma or leukemia." (PMID 24894818, 2014). "Therefore it was interesting to question whether also MRE11 and RAD50 germline mutations may increase the risk for childhood leukemia." (PMID 24093751, 2013). "In the RAD50 gene we screened four coding regions and exon-intron boundaries among leukemia patients and 504 controls." (PMID 24093751, 2013). "We estimated the frequency of constitutional mutations and polymorphisms in selected regions of MRE11, RAD50, and NBN in the group of 220 children diagnosed with childhood leukemias and controls (n=504/2200)." (PMID 24093751, 2013). "Abnormalities in a complex containing the BRCA pathway proteins MRE11, Rad50 and NBS1 (MRN complex) also associate with leukemia and lymphoma." (PMID 17683622, 2007). "Two other proteins (RAD50 and SSBP2) were very low in infant leukemia (<2 years), but then relatively similar across other age subsets with a tendency to drop again after the age of 60 years." (PMID 36982537, 2023). "Since this pathway was shown to operate in myeloid cells, we stably infected a human leukemia monocytic cell line (THP-1) with a recombinant KSHV virus (TrK.219) and used it to confirm the interaction between LANA and the Rad50-Mre11-CARD9 DNA sensor complex." (PMID 28430817, 2017).
ataxia telangiectasia (5 papers, 2015 to 2023). Ataxia-telangiectasia is the association of severe combined immunodeficiency (affecting mainly the humoral immune response) with progressive cerebellar ataxia. "ATM (mutated in ataxia-telangiectasia (A-T) and members of the Mre11/Rad50/Nbs1 (MRN complex) play key roles in this process." (PMID 26512707, 2015). "The fish model may aid in further understanding the tumorigenesis and phenotype of ataxia-telangiectasia-related RAD50 germline mutations and in developing novel therapeutic strategies against RAD50 molecular disorders." (PMID 37098078, 2023). "MRE11, RAD50, and NBS1 form the MRN complex in response to DNA damage to activate ATM, a gene responsible for Ataxia-Telangiectasia (A-T)." (PMID 35153719, 2021).
breast tumor (5 papers, 2012 to 2022). "In a cohort of 1809 breast tumours (cohort 1), low RAD50 mRNA was significantly associated with poor survival in the whole cohort (p = 0.00061) and ER− cohort (p = 0.011)." (PMID 34782604, 2021). "A total of 4 genes (RAD50, RTEL, TERC and TRF1) showed significant hyper-methylation in breast tumor tissues." (PMID 28424414, 2017).
glioma (5 papers, 2014 to 2025). A benign or malignant brain and spinal cord tumor that arises from glial cells (astrocytes, oligodendrocytes, ependymal cells). "We observed associations of methylation of RAD51 in glioma, and of RAD51C and RAD50 in CLLE." (PMID 33676569, 2021).
Hereditary breast and ovarian cancer syndrome (5 papers, 2014 to 2024). An autosomal dominant inherited syndrome caused by mutations in the BRCA1 or BRCA2 genes. "Most familial pancreatic cancer is attributable to hereditary breast and ovarian cancer syndrome that results from germline mutations in BRCA1/2 genes and other genes such as ATM, BRIP1, CHEK2, RAD50, and RAD51C." (PMID 38732320, 2024).
Immunodeficiency (5 papers, 2010 to 2025). Failure of the immune system to protect the body adequately from infection, due to the absence or insufficiency of some component process or substance. "Functional characterization of specific RAD50 missense variants would thus be important for the diagnosis of RAD50 deficiency, but also for better prediction of potential immunodeficiency, cancer risk, and cancer treatment." (PMID 41031707, 2025). "Such RAD50‐related phenotypes include different clinical characteristics in patients with the autosomal recessive syndrome RAD50 deficiency, such as immunodeficiency or cancer." (PMID 41031707, 2025). "Assessing RAD50 missense variants with distinct functional readouts may help to further elucidate their differential roles in immunodeficiency and cancer and could improve therapeutic strategies." (PMID 41031707, 2025). "Although no immune impairment has been observed in the two patients with NBSLD, some patients with A-T show immune disorders, and mutant mice with hypomorphic RAD50 showed defects in primitive hematopoietic cells." (PMID 37098078, 2023).
endometrial cancer (4 papers, 2014 to 2026). Primary or metastatic malignant neoplasm involving the endometrium (mucous membrane that lines the endometrial cavity). "As a component of the MRN complex, RAD50 mutates in acute myeloid leukemia, Burkitt lymphoma, and endometrial carcinoma." (PMID 36713553, 2022). "Immunohistochemical analysis of MRE11, RAD50, and NBS1 was successful in 456, 466, and 458 endometrial carcinomas, respectively, due to the lack of tumour tissue in some TMA spots." (PMID 24927325, 2014).
nasopharyngeal carcinoma (4 papers, 2016 to 2020). A carcinoma arising from the nasopharyngeal epithelium. "Disrupting RAD50 function has been shown to sensitize human nasopharyngeal carcinoma cells to radiotherapy." (PMID 35006434, 2020). "An adenovirus targeting RAD50 also showed promise in sensitizing nasopharyngeal carcinoma cells to radiotherapy." (PMID 30176843, 2018).
pancreatic cancer (4 papers, 2014 to 2024). "Normal vs PDAC tumour: DSB-repair functionality is severely impacted in PDAC, with inactivating mutations in RAD50 and NBS1 attributed to loss of DSB-repair functionality increasing the risk of pancreatic cancer." (PMID 25521701, 2014).
triple-negative breast carcinoma (4 papers, 2016 to 2025). An invasive breast carcinoma which is negative for expression of estrogen receptor (ER), progesterone receptor (PR), and human epidermal growth factor receptor 2 (HER2). "In line with this, RAD50 mutations compromise the functionality of BRCA1, causing an accumulation of unrepaired lesions and promoting more aggressive subtypes, such as triple-negative breast cancer." (PMID 40282418, 2025). "In this study, we presented the fundamental role of BRCA1 interactors BRIP1 and RAD50 in the development of differential severity in triple-negative breast cancer (TNBC) among various affected individuals." (PMID 36873936, 2023).
viral infection (4 papers, 2017 to 2023). "In eukaryotes, the Rad50 complex is a surveillance system for DNA ends originating from abnormal cellular physiology including viral infection." (PMID 37584323, 2023). "SMC-like complexes — bacterial Lamassu and human Rad50 — likely recognize aberrant DNA structures such as DNA ends present in plasmids or during viral infection." (PMID 37584323, 2023). "Each mutant virus infection abrogates degradation of known substrates RAD50 and MRE11." (PMID 34463575, 2021). "DNA-PKcs, IFI16, Ku70, and Rad50 are DDR proteins involved in inducing the innate immune response to viral infection, and we hypothesised that PAXX may play a similar role." (PMID 29144403, 2017). "Following viral infection or transfection with foreign DNA, CARD9 directly interacts with Rad50, a cytosolic DNA sensor, and these CARD9-Rad50 complexes subsequently recruit BCL10 to promote IL-1β secretion." (PMID 30127791, 2018).
anemia (3 papers, 2022 to 2023). A reduction in the number of red blood cells, the amount of hemoglobin, and/or the volume of packed red blood cells. "BRCA1 and 2 interacts with a number of other DNA repair proteins to form a complex system for DNA damage repair, including ATM, RAD51, PALB2, MRE11A, RAD50, NBN, and the Fanconi anemia proteins." (PMID 35785170, 2022).
cervical cancer (3 papers, 2018 to 2024). A primary or metastatic malignant neoplasm involving the cervix. "Furthermore, this is the first discovery of the RAD50 p.Q975Lfs*6 frameshift mutation in cervical cancer." (PMID 38950928, 2024). "When examining levels of MMR proteins individually, we found that MSH-2 low independently predicted poor outcome in cervical cancer and that MSH-2 low associated with higher mutational burden, RAD50 frameshift mutations, and an immune reactive transcriptome." (PMID 38950928, 2024). "A possible link between RAD50 and the MMR system should be further investigated in cervical cancer." (PMID 38950928, 2024).